MMP7 (matrix metallopeptidase 7)
Diseases named in the same sentence as MMP7 in open-access papers (continued):
Sharing a sentence is not in itself a finding about the gene and the disease.
tumor (continued). "At the molecular level, the high-risk score group had elevated expressions of tumor enhancing factors, including MMP7, and SFRP2, which may synergistically promote tumor growth, proliferation, invasion and chemoresistance." (PMID 36907877, 2023). "Therefore, we noted the presence of MMP7 and three calpain components, CAPN1, CAPN2, and CAPNS1, as tumor-derived EV protein cargo." (PMID 36470535, 2023). "However, the available data seem to describe a complex picture in relation to different MMP types: MMP-7 cleaves type-XVIII collagen to endostatin and plasminogen to angiostatin, thus potentially inhibiting angiogenesis and, consequently, tumor growth." (PMID 37445908, 2023). "such as MMP7 related to ECM components, highly expressed in tumor cells in the responder." (PMID 37152010, 2023). "Furthermore, we explored the TMN plot to compare VEGFA, CTNNB1, MMP7, and CD44 oncogenes in tumor and metastatic CRC samples from RNA sequencing data (RNAseq)." (PMID 36672201, 2023). "Expression in tumor cells was also scored as 1 in 10 sections (33.3%), but the majority did not express MMP-7 (n = 19, 63.3%)." (PMID 35884455, 2022). "Higher serum MMP-7 levels were found in muscle-invasive and high-grade tumours, but these correlations were not significant (p = 0.140 and p = 0.077)." (PMID 35327500, 2022). "Moreover, Western blot analyses also showed a 36.56% reduction in MMP7, and 39.45% reduction in β-catenin in the PANC1 tumor-bearing mice that received hAFMSCs injection compared to PBS-treated PANC1 tumor-bearing mice (P < 0.05)." (PMID 35659367, 2022). "Mice without tumor cell implantation had serum MMP7 levels below 43.33 ± 2.10 pg/ml (control), whereas at 3 months following PANC1 tumor cell implantation, MMP7 levels were significantly higher (93.29 ± 12.62 pg/ml; PANC1 alone group)." (PMID 35659367, 2022). "MMP-7 and MMP-9 belong to the MMP family and are capable of cleaving extracellular matrix proteins (ECMs), which participate in various tumorigenesis activities such as tumour progression and metastasis." (PMID 35783514, 2022). "Both MMP7 and LCN2 are critical for cell migration, tumor invasion, and metastasis." (PMID 36551599, 2022). "In vivo, β-catenin, Cyclin D1 and Mmp7 clearly designated tumor from normal colon; however, no downregulation of Wnt/β-catenin targets was observed with dietary SPI intake." (PMID 35159382, 2022). "The tumor sections with the first antibody anti-MMP-7 omitted and incubated with PBS (negative control) did not exhibit positive staining." (PMID 36518899, 2022). "The authors further determined that WNT5A induces Matrilysin (MMP7) through a non-canonical Nuclear factor (NF)-κB signaling pathway, which drives tumor metastasis in mice." (PMID 34298659, 2021). "An enforced expression of MMP-7 in PrCa cells has been shown to mediate an increased invasion, while a mouse MMP-7 knockout model exhibited reduced tumor-induced osteolysis, indicating the source of this enzyme may not be critical." (PMID 33808504, 2021). "In addition, MMP‐2, MMP‐7 and MMP‐9, the target genes of Wnt/β‐catenin signaling, function to degrade extracellular matrix and basement membrane to promote tumor cell metastasis." (PMID 34165914, 2021). "An immunohistochemical study of MMP-7, -14 and TIMP-1 was performed on sporadic CRC (n = 86), IBD-associated CRC (n = 23) and colorectal mucosa of non-tumor samples from IBD patients without (n = 47) and with (n = 23) associated CRC." (PMID 33946534, 2021). "The active MMP7 can also cleave the pro-MMP2 and pro-MMP9 to facilitate tumor invasion." (PMID 33936204, 2021). "Finally, MMP7 is a metalloprotease involved in ECM physiology, epithelial-mesenchymal transition, and tumor invasion that is overexpressed in some cancer types." (PMID 34233687, 2021). "Therefore, the aim of the present study was to determine plasma levels of MMP-7 and MMP-26 in comparison to the commonly accepted tumour marker (CA 15-3) in various stages of BC." (PMID 33916127, 2021).
tumor (continued). "We found that MMP1, MMP3, MMP7, MMP9-MMP12, and MMP14 were significantly upregulated in tumor tissue, while MMP15–MMP17, MMP19–MMP21, MMP23A, MMP23B, and MMP25–MMP28 were significantly downregulated in tumor tissue." (PMID 34804973, 2021). "In addition, during tumor invasion and metastasis, MMP-2, MMP-7, and MMP-9, the target genes of Wnt/β-catenin signaling, function to degrade the ECM and basement membrane so that tumor cells can detach, invade, and metastasize." (PMID 33542902, 2020). "In this context, MMP-7 expression has been inversely correlated to syndecan-1 abundance, indicating a role of MMP-7 in shedding the protein, a function which is beneficial for wound healing but harmful with respect to tumor progression." (PMID 32796709, 2020). "Proto-oncogenes are those genes that are involved in cell growth and proliferation, with potential examples including the ATM, FGFR2, FN1, IGF1, MAP3K, MMP7, and RHOC genes, while the CASP8 and LSP1 genes have been reported to possess tumor-suppressive properties in certain types of cancer." (PMID 33112566, 2020). "Overall, concomitant positive expression of MMP-7 and TIMP-1 might comprehensively evaluate the state of tumour progression and predict the prognosis of patients with GC." (PMID 33005257, 2020). "In addition, chronic stress increased the expression of VEGF, MMP-2, MMP-7 and MMP-9 in transplanted tumour tissue, and catecholamine hormones enhanced the expression of metastasis-related proteins." (PMID 31624248, 2019). "AURKA overexpression could also increase the expression of MMP-2, MMP-7, MMP-9, leading to tumor metastasis by degrading extracellular matrix proteins." (PMID 31706255, 2019). "A potential explanation of this result could be an indirect effect of MesobsFab on the MSLN-driven secretion of matrix metalloproteases, notably MMP-7 and MMP-9 which have been described as promoting tumor invasion." (PMID 31354732, 2019). "Additionally, MMP7 is able to convert proMMP2 to active MMP2 and proMMP9 to active MMP9 thereby facilitating macrophage-tumor-stromal cell cross-talk." (PMID 29581841, 2018). "Consistent with our theory, the protein expression of MMP7 and CCND1 were downregulated in a SOX30-overexpressing cell line and xenograft tumors; MMP7 and CCND1 expression were increased significantly in SOX30-overexpressing cells, or tumor tissue after DSP or JUP expression was blocked." (PMID 29855376, 2018). "An inhibitor of MMPs, including MMP7 and MMP9, was shown to suppress tumour metastasis." (PMID 29631554, 2018). "High MMP7 expression was found in tumor tissue while E-cadherin expression was not altered (P>0.05)." (PMID 28796798, 2017). "Taken together, our findings indicated that SLC12A5 might function as a tumor metastasis promoting factor in the development and progression of BUC by regulating the NF-κB/MMP-7 signaling pathway." (PMID 28333147, 2017). "In this complex, MMP-7 processes HB-EGF precursor and the resultant HB-EGF activates and stimulates its receptor, ErbB4, resulting in the destruction of the basement membrane, which is an essential step towards tumor progression." (PMID 27271600, 2016). "In conclusion, our findings confirmed that MMP-2, MMP-7, and MMP-9 may take part in various morphological features of PDAC tumor." (PMID 27429508, 2016). "Our findings suggest that MMP-7 expression in PDAC cancer cells may contribute to the degradation of the peritumoral stroma, thus facilitating tumor cell invasion and metastasis." (PMID 27429508, 2016). "Moreover, MMP-10 up-regulates several other MMPs such as MMP-1, MMP-7, MMP-9, and MMP-13 that are essential for tumor progression." (PMID 27271600, 2016). "Herein, we report that further to the previously published findings on PG545′s ability to interfere with angiogenic growth factors, this compound also inhibits Wnt signaling within tumor cells which leads to reduced levels of β-catenin, VEGF, MMP-7 and Cyclin D1." (PMID 25669977, 2015).
tumor (continued). "The preponderant phenotype observed in tumor stroma is a tumor promoting phenotype characterized by the expression of molecules promoting angiogenesis (e.g., VEGF-C, IL-8), tumor growth (TNF-α) and invasiveness (MMP-7, MMP-9)." (PMID 31557983, 2015). "Interestingly, components of the Wnt signaling pathway, including MMP-7, β-catenin, and APC, were significantly upregulated in high 5-HT1D R tumor tissue, implying a possible link between 5-HT1D R and Wnt signaling pathway in CRC patients." (PMID 26214021, 2015). "Similarly, CXCL5, CXCL13, CCL1, CCL7 and CCL26 in WF collected from patients with T1–2 tumor tend to be higher than those with Tis, and the profiles of CXCL13, CCL27, MMP-1 and MMP-7 in WF from N1–3 patients tend to be higher than those with N0." (PMID 26313265, 2015). "We have used a use a newly employed marker gene, expressed in all cancer cells and not detectable in any non-tumor cells, the MMP-7." (PMID 25596746, 2015). "In addition, the enzymatic activity of MMP-7 in degrading ECM potentially contributes to the invasion and metastasis of tumor cells by increasing proliferation, by hydrolyzing the ECM and promoting migration and angiogenesis, and by affecting cell apoptosis." (PMID 25823818, 2015). "Expression of p-mTOR, pS6, p4EBP1, and MMP7 was elevated in primary tumor tissue as compared with that in adjacent noncancerous gastric tissue." (PMID 25909163, 2015). "In patients with solid tumors, serum level of MMP7 does not seem to correlate strongly with tumor tissue level of MMP7." (PMID 25919283, 2014). "According to the well-documented role of MMP-7, IL-8, and VEGFA for cancer development and tumor growth, synergistic effects between HH/EGF mediated signaling pathways may accelerate tumor initiation and support tumor growth." (PMID 23762360, 2013). "MMP-7 is not expressed by keratinocytes in normal epidermis or in cutaneous wounds, but it is expressed by tumor cells in cutaneous SCCs." (PMID 22427941, 2012). "This seems to be tumor type specific, however, since most cervical neoplasia and carcinoma cases were found negative for MMP-7." (PMID 22863036, 2012). "Two of the 31 most differentially expressed genes between the ESR1-negative and ESR1-positive BRCA1 tumours, CD133 and MMP7, were evaluated by immunohistochemistry and immunofluorescence in an independent series of 15 BRCA1 tumours, previously classified as basal or luminal." (PMID 19826428, 2009). "In a random series of 110 HCC patients, the mRNA of HIF-1alpha, inflammation related factors (COX-2, MMP7 and MMP9), angiogenesis related factors (VEGF and PDGFRA) and MYC in tumor tissue were detected by real-time RT-PCR and HIF-1alpha protein was assessed by immunohistochemistry." (PMID 19948069, 2009). "MMP7 has been widely studied in cancer progression not only by its implication in ECM degradation and metastasis promotion, but also by its role in the Fas/FasL system regulation and in the apoptosis responsiveness of tumor cells." (PMID 19266094, 2009). "The maximum separation between tissue types (normals, as opposed to tumour tissue plus cell lines) occurred with the transcript combination of MMP-7, RECK and SLC5A8." (PMID 19689820, 2009). "The fact that tumours of the AG/GG patients did not contain higher MMP-7 antigen levels in our study suggests that the presence of SNP MMP-7−181A>G alone is not directly translated into an enhanced tumour MMP-7 antigen expression or activity." (PMID 16940985, 2006). "However, the superior sensitivity and yield of serum MMP‐7 levels over SDC1 in PDAC, suggests that it may be the dominant modulator in tumor progression and microenvironment, possibly thorough several mechanisms of which one is the release of SDC1 ectodomain." (PMID 39263943, 2024). "Additionally, MMP-7 promotes tumor invasion through its role in the regulation of non-ECM components." (PMID 37513440, 2023). "Also, MMP-7 activation of pro-MMP-2 and -9 can facilitate tumor invasion." (PMID 37513440, 2023).
tumor (continued). "Therefore, CEMIP may have a positive correlation with MMP2, MMP7, MMP13, and MMP14 and regulate tumor cell EMT through MMPs to promote tumor cell migration." (PMID 37662915, 2023). "Furthermore, a protein–protein interaction analysis obtained from the STRING website showed a direct interaction between SPP1 and CD44, MMP3, MMP7, TIMP1 and fibronectin-1, all of which are directly involved in the extracellular matrix remodeling and promotion of tumor metastasis." (PMID 38067407, 2023). "However, the increased proliferative ability with MMP7 OE thus suggests that MMP7 facilitates tumor spread but no self‐renewal." (PMID 32761892, 2022). "The correlation of MMP-7 expression with clinicopathological characteristics, including tumor location, tumor size, histologic type, lymphatic invasion, vascular invasion, pathological T stage, pathological TNM stage, residual tumor, and CEA level, was investigated." (PMID 35496040, 2022). "Additionally, the tumor markers, which were found in the circulating system, could be CA19-9, α1β-glycoprotein, afamin, MMP-7, HYP, collagen I and γ-Glutamyltransferase, etc.." (PMID 34680259, 2021). "In addition, impaired MMP7, MMP9, and ADAM9 expression were found in ALOC-EO-treated B16F10 cells in a dose-dependent manner in vitro indicating that ALOC-EO suppresses the expression of tumor cell-derived proteases." (PMID 34360915, 2021). "Instead, tumor-specific and context-dependent activation of subset of genes with distinct functions (e.g., SPARC, FN1, MMP7, ZEB1, ECM1) synergistically promoting, for example, collective cell migration upon interaction with the stromal microenvironment, may represent a more likely scenario." (PMID 34036938, 2021). "Therefore, we speculate that coexpression of MMP-7 and TIMP-1 in tumour tissue may initiate a positive feedback pathway that directly accelerates tumour invasion and progression." (PMID 33005257, 2020). "Backcrossing gal-1−/− mice in RAG−/− mice, which was previously used to point out the contribution of stromal MMP-7 to the osteolytic process, also results in immunodeficient mice lacking B and T-cell responses that may influence tumour take and development." (PMID 30813402, 2019). "We also demonstrated the anti-tumor mechanism by which GXI could induce HepG2 apoptosis via the mitochondrial pathway and had the ability to inhibit HepG2 cell migration by downregulating the expression of MMP-7 and MMP-9." (PMID 31569691, 2019). "Two of them, MMP7 and MMP9, were reported that higher expression of the two genes with poor prognosis of ccRCC19,20, supporting our results that higher expression of the two genes with poor survival probability, higher neoplasm histologic grade and pathologic stage." (PMID 31723226, 2019). "Notably, no increase in MMP7 expression was detected by RT–PCR, suggesting that the increased levels of MMP7 detected in the plasma of tumor‐bearing mice might reflect a systemic response of the host to the tumor, in line with the known association of MMP7 with inflammation." (PMID 29941541, 2018). "After eight treatments, TIMP1, MMP7, and TSP2 were significantly lower (P < 0.05) in the responding (gemcitabine + NAB‐P group) compared to the non‐responding tumors (gemcitabine group), thus suggesting they were potential markers for monitoring tumor response and treatment efficacy." (PMID 29941541, 2018). "Moreover, we observed a strong, negative relationship between MMP-7 expression in tumor cells and MVD." (PMID 27429508, 2016). "MMP-7 is one of the few MMPs that is secreted by tumor cells, but not stromal cells." (PMID 25823818, 2015).
tumor (continued). "As would be expected, TAMs possess M2-like traits; Tumour cells and the tumour microenvironment release a variety of factors that facilitate this, including IL-4, IL-6, IL-10, PGE2, TGF-β1 and CSF-1, expressed by tumour cells, as well as IL-10, PGE2 and MMP-7 expressed by TAMs." (PMID 22005011, 2011). "MMP-7 is the smallest protein in the MMP family but possesses the highest extracellular matrix (ECM)-degradative activity against a variety of ECM components; thus, it is capable of triggering the activation of an MMP cascade and is related closely to tumor invasion and metastasis." (PMID 21991388, 2011). "Another possible explanation for this may originate from the immunohistochemical observation that enhanced MMP-7 expression is frequently localized to the tumor–normal and tumor–stoma interface, suggesting that an interaction with non-malignant cells is necessary for the expression of MMP-7." (PMID 33396213, 2020). "However, the immune-reactivity score for mTOR was higher in the tumor center of patients with evidence of distant metastases (p = 0.01), and MMP7 was more highly expressed in the tumors of patients with nodal involvement (tumor center: p = 0.01, invasive front: p = 0.019; data not shown)." (PMID 26652716, 2015). "Nevertheless, MMP-7 might not regulate tumor cell metastasis via direct degradation of ECM." (PMID 25823818, 2015). "Our results that MMP-7 and MMP-13 were absent from areas of diffuse invasion and high malignancy, in good correlation with Bryne's malignancy grading of tumour structure and nuclear polymorphism, suggest that together these two MMPs might be useful as predictive markers of invasiveness in OSCC." (PMID 26019601, 2014). "MMP-7 mRNA was present in tumor tissues, but could not be detected in normal control tissues." (PMID 22159423, 2012). "Finally, absence of MMP7 may result in a significant reduction in mean tumour number and average tumour diameter in Min (multiple intestinal neoplasia) mice deficient in this MMP." (PMID 17125518, 2006). "A recent study using RNA sequencing and immunohistochemistry revealed an overexpression of C-type lectin domain family 3 member A (CLEC3A), matrix metallopeptidase 7 (MMP7) and lipocalin 2 (LCN2) in recurrent PanNETs compared to non-recurrent tumor." (PMID 36551599, 2022). "Unlike common anticancer agents, BB94 is a potent extracellular inhibitor of MMP-1, MMP-2, MMP-3, MMP-7, and MMP-9, and thus, it should be released in the extracellular space rather than in tumor cells." (PMID 35440570, 2022). "Accordingly, the downregulation of CD147 resulted in lack of expression of its downstream target MMP7 and correlated with lack of engraftment of ALK+ ALCL cells or striking tumor growth retardation." (PMID 35676454, 2022). "ALOC-EO-treated, but not control B16F10 tumor-carrying mice showed lower total MMP9 plasma levels and a lower MMP7 and MMP9 gene expression in extracted tumors." (PMID 34360915, 2021). "The expression levels of MMP7 (P = 0.0123) and MMP13 (P = 0.0147) were significantly increased in the metastatic tumour samples, while that of MMP10 (P = 0.0932) was not." (PMID 31996191, 2020). "In HCC, increased transcriptional activity of MMP7 and ETS1 as compared with adjacent noncancerous liver tissue statistically correlated with tumor progression of HCCs." (PMID 32977498, 2020). "MMP7, MMP13, and MMP10 were significantly upregulated, while MMP12 and MMP9 were downregulated in metastatic tumour samples compared with nonmetastatic tumour samples." (PMID 31996191, 2020). "The intravenous administration of PB-M7NIR in mice allowed for selective tumor visualization and localization with two point two-fold improved signals in MMP7 SW480 tumors relative to MMP7-negative tumors." (PMID 25988156, 2014).